QKILA (QKI interacting lncRNA)
Synonyms: Loc490
Gene: Long non-coding RNA gene on chromosome 4 (139,564,295 to 139,666,068, reverse strand). Ensembl gene ENSG00000261268.
Diseases named in the same sentence as QKILA in open-access papers:
QKILA is named in the same sentence as 2 diseases in open-access papers, as found by Europe PMC text mining. Sharing a sentence is not in itself a finding about the gene and the disease.
QKILA shares sentences with these, for which no sentence is quoted: lymph node metastasis (1 paper); tumor (1).